TFRC (transferrin receptor)
Diseases named in the same sentence as TFRC in open-access papers (continued):
Sharing a sentence is not in itself a finding about the gene and the disease.
prostate carcinoma (24 papers, 2013 to 2025). A carcinoma that arises from epithelial cells of the prostate gland. "Some other candidate genes are less well studied but associated to CRC and gastric- as well as prostate cancer: TFRC." (PMID 39543761, 2024). "Increasing transferrin receptor protein 1 (TfR1) levels and progressive ferroportin downregulation have been associated with transforming primary tumors to metastatic cancer in prostate cancer." (PMID 37021836, 2023). "Transferrin receptor levels have been previously shown to be elevated in prostate cancer patients in association with altered iron metabolism, and has been proposed as a ferroptosis-related biomarker." (PMID 38053024, 2023). "Similarly, gastric cancer and prostate cancers models have shown that TFRC overexpression is associated with increased tumor incidence and aggressiveness, suggesting a direct link between iron uptake and cancer progression." (PMID 40303995, 2025). "Moreover, increased levels of the TfR1 importer protein, encoded by the TFRC gene, have been reported in prostate cancer cell lines, improving intracellular iron uptake." (PMID 35447901, 2022). "An alternative strategy for FZD6 inhibition is to conjugate siRNA targeting FZD6 with aptamers directed against prostate cancer antigens such as PSMA (prostate-specific membrane antigen) or TfR1 (Transferrin Receptor 1)." (PMID 41286306, 2025). "SPH co-administered with bicalutamide demonstrated the significant up-regulation of FTH1 and down-regulation of TFRC, a gene expression profile unfavorable for further prostate cancer cell growth." (PMID 35447901, 2022). "Since prostate cancer shows significantly increased iron uptake, presenting thus upregulation of transferrin receptor, TfR1 has been early introduced as a marker of transformed prostate cell phenotype." (PMID 34884287, 2021). "TFRC is annotated with the following 8 terms: brain, erythroleukemia, eye, human endometrium carcinoma cell line, kidney, pancreas, placenta, and prostatic carcinoma." (PMID 25419056, 2014). "TFRC has been proposed as a tumor biomarker in a wide spectrum of malignancies, including B-cell lymphoma, pancreatic, esophageal, cervical as well as prostate cancers." (PMID 23846725, 2013). "Furthermore, studies have indicated that the combination of TFRC-targeting agents with existing chemotherapy regimens can enhance the overall efficacy of treatment, particularly in resistant cancer types such as breast and prostate cancer." (PMID 40303995, 2025). "Selected ARA-lincRNAs are neighbors of protein-coding genes WDR5, ZNF706, TFRC, and FLNA, which have been described as up-regulated in prostate cancer, and of CENPH and RAB11FIP3, which have been shown to play a role in many other types of cancer." (PMID 29875794, 2018). "A prostate cancer-specific tumor biomarker is the prostate-specific antigen (PSA), while an indicator of intracellular iron concentration and storage is the soluble transferrin receptor (sTfR)." (PMID 36895478, 2023).
Immunodeficiency (21 papers, 2018 to 2025). Failure of the immune system to protect the body adequately from infection, due to the absence or insufficiency of some component process or substance. "Missense mutations of the CD71 gene, TFRC, causes immunodeficiency and defective T cell proliferation, showing that CD71 expression and the resulting iron flux are important for T cell activation." (PMID 37445926, 2023). "A recent study demonstrated that patients and a mouse model with a homozygous mutation in TFRC showed combined immunodeficiency characterized by decreased proliferation of T and B cells and defective class switching." (PMID 35847985, 2022). "Immune deficiency characterized by impaired lymphocyte development and function is due to gene mutation of transferrin receptor 1 (CD71), which affects the internalization of iron-transferrin complex." (PMID 35401569, 2022). "Impairment and dysfunction of B cells due to the mutation of transferrin receptor 1 (TfR1) encoded by TFRC cause combined immunodeficiency." (PMID 35401569, 2022). "ID impairs B-cell proliferation and antibody production, and a mutation in transferrin receptor 1 (TfR1), which causes insufficient cellular iron uptake, leads to defective B- and T-cell activation and combined-immunodeficiency." (PMID 32507899, 2021). "Recently, both patients and a mouse model with a homozygous mutation in TFRC exhibited combined immunodeficiency, which is characterized by impaired proliferation of T and B cells and defective class switching, which is essential for antibody production." (PMID 34518441, 2021). "For example, lymphocyte deficiency in iron transport due to a polymorphism in the human TFRC gene, is linked to a severe immunodeficiency phenotype with a low proliferative response in vitro to mitogen stimulation." (PMID 31921164, 2019). "The GSEA analysis unveiled TFRC involvement in regulating the malignant phenotype of CC, as well as its participation in pathways linked to immune deficiency, the JNK pathway, chromosome condensation, the RHOC GTPase cycle, and ECM receptor interactions associated with invasive functions." (PMID 39131609, 2024). "Furthermore, a mutation in TFRC that reduces efficiency of extracellular iron uptake by ~50% causes severe immunodeficiency in children." (PMID 34880854, 2021). "Importantly, a mutation in the human TFRC gene, which codes for TFR, was identified in patients with combined immunodeficiencies (CID)." (PMID 31824960, 2019). "In terms of B cell function, it has been proven that the dysfunction of these cells can happen due to the mutation of transferrin receptor 1 (TfR1) encoded by TFRC and can lead to immunodeficiency." (PMID 38612580, 2024). "Further, children bearing an amino acid change in the transferrin receptor, that impairs cellular iron uptake, display severe combined immunodeficiencies featuring hypogammaglobulinemia and defective lymphocyte proliferation." (PMID 34880854, 2021). "As a consequence, mutations in the gene coding for transferrin receptor-1, TFRC, can cause combined immunodeficiency characterized by impaired function of B and T lymphocytes." (PMID 33344239, 2020). "The GSEA analysis revealed a predominant concentration of the TFRC gene expression phenotype in the ferroptosis, diseases of immune system, jak stat signaling pathway, ECM affiliated, RHO GTPases activate NADPH oxidases, JNK pathway, and condensation of chromosomes." (PMID 39131609, 2024). "Additionally, loss of TFRC, the gene encoding for CD71, has been demonstrated to cause a combined immunodeficiency in two families." (PMID 30028872, 2018). "Three of the factors were expressed at higher levels in ambiguous than in unambiguous cases—AHSG, TFRC, DHX9—and are involved in inflammation, innate immunity, and immunodeficiency, which are components of past infections." (PMID 33582300, 2021).
neuroblastoma (21 papers, 2007 to 2024). Neuroblastoma (NB) is the most common solid, extracranial childhood tumor. "Since melanoma and neuroblastoma have the same embryological neuroectodermal origin, we investigated whether neuroblastoma cell lines have the same susceptibility to vitamin C. First we studied the expression of transferrin receptor in neuroblastoma cell lines." (PMID 17760959, 2007). "However, some reports found that the ferroptosis-related molecular TFRC can induce the activation of ferroptosis in neuroblastoma (NB)." (PMID 36483569, 2022). "Inhibition of transferrin receptor (TfR) prevented the overexpression and aggregation of α-Syn in response to 1-methyl-4-phenylpyridinium (MPP+) treatment in neuroblastomas." (PMID 39201524, 2024). "Further studies revealed that the transferrin receptor 1 was upregulated in response to such MYCN amplification, leading to increased GPx4 sensitivity and rendering neuroblastoma cells vulnerable to ferroptosis induction." (PMID 34926298, 2021). "mRNA expression levels of MYCN, ΔMYCN and MYCNOS were measured in 16 human neuroblastoma samples by QPCR relative to three reference genes: GUSB, TFRC and RNFIII." (PMID 19615087, 2009). "In a differentiated human neuroblastoma cell line (SH-SY5Y), endogenous ClC-6 colocalizes with LAMP-1, a late endosomal/lysosomal marker, but not with early/recycling endosomal markers such as EEA-1 and transferrin receptor." (PMID 17534424, 2007).
Sepsis (21 papers, 2017 to 2025). Sepsis is defined as life-threatening organ dysfunction caused by a dysregulated host response to infection. "Similar with our outcomes, regulation of TFRC-related axis promotes ferroptosis in sepsis-associated encephalopathy." (PMID 39251905, 2024). "In the analysis of iron metabolites and sepsis, there were 2 SNPs in SI, 86 SNPs in SF, 4 SNPs in STF, 4 SNPs in TFRC, and 29 SNPs in TSP; and SF was a risk factor of sepsis (OR = 3.079, 95%CI: 1.420~6.679, P = 0.004)." (PMID 41323136, 2025). "Genome-wide association studies (GWAS) data for SI, serum ferritin (SF), serum transferrin (STF), transferrin receptor (TFRC), sepsis, and cardiomyopathy were obtained from the EBI website." (PMID 41323136, 2025). "NAT10 was also found promoting sepsis-induced pulmonary injury by mediating ac4C acetylation of TFRC mRNA." (PMID 40588654, 2025). "Our study, for the first time, discovered the regulatory effects of glycolysis‐derived H3K14la on ferroptosis in sepsis‐induced lung injury and revealed that H3K14la activated ECs by modulating the gene transcription of TFRC and SLC40A1." (PMID 39822760, 2025). "Transferrin receptor 1 (TfR1) mediates iron entry, and its upregulation in sepsis-induced ARDS correlates with ferroptosis markers." (PMID 41383584, 2025). "miR-9-5p alleviates sepsis-induced ferroptosis by inhibiting the expression of TFRC and GOT1 in vivo." (PMID 37008225, 2023). "We investigate the ceRNA axis NEAT1/miR-9-5p/TFRC/GOT1 on sepsis-induced ferroptosis for the first time in the present study." (PMID 35038133, 2022). "In the present study, we found that miR-9-5p alleviated sepsis-induced neurons ferroptosis by suppressing the expression of TFRC and GOT1." (PMID 35038133, 2022). "GPX4 and TFRC played an important role in ferroptosis, so it was necessary to analyze the difference between sepsis and control." (PMID 35844488, 2022). "The present study provided a clue for SAE of sepsis-induced ferroptosis through axis NEAT1/miR-9-5p/TFRC and GOT1." (PMID 35038133, 2022). "Increased miR-9-5p alleviated sepsis-induced ferroptosis by suppressing the expression of TFRC and GOT1 both in vivo and in vitro." (PMID 35038133, 2022). "Furthermore, in the analysis of iron metabolites and sepsis, there were 2 SNPs in SI, 86 SNPs in SF, 4 SNPs in STF, 4 SNPs in TFRC, and 29 SNPs in TSP; and SF was a risk factor of sepsis (OR = 3.079, 95%CI: 1.420~6.679, P = 0.004)." (PMID 41323136, 2025). "The present study aimed to figure out whether exosomal lncRNA NEAT1 affects sepsis-induced ferroptosis through NEAT1/miR-9-5p/TFRC and GOT1 axis." (PMID 35038133, 2022). "on sepsis-inducing plasmacytoid exosome-derived lncRNANEAT1 suggest that it may promote ferroptosis by modulating the miR-9-5p/transferrin receptor (TFRC) and glutamic-oxaloacetic transaminase 1 (GOT1) axes, ultimately exacerbating SAE." (PMID 35990689, 2022). "Therefore, TFRC might participate in sepsis-induced ferroptosis by increasing the iron content in cells." (PMID 35038133, 2022). "During sepsis, lactate‐dependent H3K14 lactylation at the promoter regions of ferroptosis‐related genes (TFRC, SLC40A1) promoted ferroptosis in ECs, which drives vascular dysfunction in sepsis‐related ARDS." (PMID 39822760, 2025). "Recent studies reveal that sepsis-induced hypoxia upregulates hypoxia-inducible factor-1α (HIF-1α), which increases cellular iron uptake via transferrin receptor 1 (TfR1)." (PMID 40893878, 2025). "We found that exosomal NEAT1 transported into the cerebral cortex and functions as a ceRNA for miR-9-5p to facilitate TFRC and GOT1 expression, therefore, play important roles in sepsis-induced ferroptosis and SAE." (PMID 35038133, 2022). "Therefore, DEFA4, ELANE, MPO, and TFRC might be related to immune paralysis in sepsis." (PMID 36532037, 2022). "Sepsis induced high expression of serous exosome-derived NEAT1, which might exacerbate SAE by regulating the miR-9-5p/TFRC and GOT1 axis to promote siderosis." (PMID 37008225, 2023).
Sepsis (continued). "However, sepsis cases with increased levels of mRNA of DHCR7, GABARAPL2, MAOA, MPO, PDZD8, and TFRC had worse overall survival." (PMID 38011291, 2023). "Taken together, the result revealed that miR-9-5p, sponged by NEAT1, targeted TFRC and GOT1 that overexpressed in vitro and in vivo and might promote sepsis-induced ferroptosis in brain microvascular endothelial cells." (PMID 35038133, 2022). "In conclusion, these findings suggest that sepsis induced high expression of serous exosome-derived NEAT1, and it might exacerbate SAE by promoting ferroptosis through regulating miR-9-5p/TFRC and GOT1 axis." (PMID 35038133, 2022).
gastric cancer (20 papers, 2012 to 2026). A primary or metastatic malignant neoplasm involving the stomach. "In our study, we investigated whether there was an effect modification of the association between dietary iron intake and gastric cancer risk by TFRC genetic polymorphism." (PMID 34444760, 2021). "Here, we identify artesunate, an antimalarial drug, as a potent inducer of ferroptosis in gastric cancer cells and reveal the transferrin receptor (TFRC) as a key mediator in this process." (PMID 40946428, 2025). "Overall, these results provide strong evidence that ART directly binds to TFRC, preventing its lysosomal degradation and thereby modulating iron homeostasis to promote ferroptosis in gastric cancer cells." (PMID 40946428, 2025). "By identifying TFRC as a critical mediator in this process, we offer insights into artesunate's potential for overcoming resistance in gastric cancer treatment." (PMID 40946428, 2025). "In this study, we demonstrate for the first time that artesunate induces ferroptosis in gastric cancer cells through its regulation of TFRC, specifically by stabilizing TFRC expression and inhibiting HSPA9-mediated lysosomal degradation of TFRC." (PMID 40946428, 2025). "Transferrin receptor expression was checked on gastric cancer/tumortissues in relation to normal gastric tissues." (PMID 34778662, 2021). "AbGn107, an ADC based on an anti-CD71 (transferrin receptor 1) antibody is currently in phase I clinical trials to treat colorectal, pancreatic and stomach cancers." (PMID 29409507, 2018). "To explore whether there is a correlation between TFRC expression and sensitivity to artesunate in gastric cancer, we conducted an initial analysis of TFRC expression across five gastric cancer cell lines." (PMID 40946428, 2025). "Several studies in gastric cancer (GC) have shown that the expression of TFRC is reversely correlated with a poor prognosis in primary GC." (PMID 37675227, 2023). "To investigate the impact of ART on TFRC, we first assessed TFRC mRNA levels in MGC-803 and MKN45 gastric cancer cells treated with artesunate." (PMID 40946428, 2025). "This study provides a comprehensive model of how artesunate leverages TFRC stabilization and HSPA9 inhibition to induce ferroptosis in gastric cancer cells." (PMID 40946428, 2025). "With this interaction characterized, we then explored the regulatory relationship between TFRC and HSPA9 by modulating HSPA9 expression in gastric cancer cells." (PMID 40946428, 2025). "Furthermore, HFn's natural affinity for transferrin receptor 1 (TfR1/CD71)—a receptor overexpressed in multiple cancer types, including gastric carcinoma—renders it an ideal candidate for targeted delivery." (PMID 41567734, 2026). "Regarding the mechanisms of iron entry into gastric cancer cells, transferrin receptor (TfR) expression does not differ significantly from normal gastric tissue, but recent studies suggest that TfR could be a novel prognostic marker and therapeutic target." (PMID 38370477, 2024).
melanoma (20 papers, 2007 to 2025). A malignant, usually aggressive tumor composed of atypical, neoplastic melanocytes. "In B16F10 mouse melanoma cells, high-dose ascorbate led to the induction of caspase-8-independent apoptosis via decrease in transferrin receptor-dependent cellular iron uptake." (PMID 36672190, 2023). "Our experiments revealed an increased expression of transferrin receptor 1 (TfR1) and a significant decrease of cancer cell viability, indicating the bacteria’s ability to alter iron homeostasis in human melanoma cells." (PMID 33419059, 2021). "As reported in the literature, TBC1D16 as a driver of melanoma is a Rab4A GAP that is engaged in the trafficking of transferrin receptor and EGFR." (PMID 33194704, 2020). "Mouse melanoma cells, which strongly express the transferrin receptor, were exposed to PDA/Tf nanoparticles (NPs) and, subsequently, were irradiated with a UV laser." (PMID 30562983, 2018). "This is the case for both the integrins here described, but also the transferrin receptor —all used as melanoma targets." (PMID 23634303, 2013). "Sodium ascorbate has been recently reported to induce apoptosis of B16 melanoma cells through down-regulation of the transferrin receptor, CD71." (PMID 17760959, 2007). "ACTB, hypoxanthine phosphoribosyltransferase 1 (HPRT1), TATA-box binding protein (TBP) and transferrin receptor (TFRC) genes were reported to show a minimal average variation in FFPE and frozen tissue samples of melanoma and other diseases." (PMID 34940125, 2021). "Nevertheless, the fact that the authors used a delivery vector targeting the transferrin receptor without showing analysis of such receptor expression in melanoma cells was left to be explained." (PMID 23634303, 2013).
Stroke (20 papers, 2013 to 2025). Sudden impairment of blood flow to a part of the brain due to occlusion or rupture of an artery to the brain. "In stroke patients, ferroptosis is associated with stroke severity and outcomes, correlating with higher 4-hydroxynonenal and lower soluble transferrin receptor levels.This form of cell death primarily affects neurons and has garnered significant attention due to its implications for IS." (PMID 40890801, 2025). "In a mice model of stroke, it was found that SeNPs enter brain cells via transferrin receptor-mediated endocytosis, inhibit the inflammatory response, and increase the survival of hippocampal neurons." (PMID 36432668, 2022). "As NEDD4L suppresses ferroptosis and iron-mediated neuronal death after stroke by ubiquitinating the iron transporter TFRC, we explored whether boosting METTL3 could protect the brain against ischemia through modulating the NEDD4L-TFRC pathway." (PMID 38302612, 2024). "The reason of this result might be due to the increased expression of the transferrin receptor on the BBB due to stroke." (PMID 30949500, 2019). "This may reflect a need for sustained delivery and transport of BDNF into the CNS parenchyma, as either stem cell-mediated delivery, or systemic delivery of BDNF conjugated to a BBB transferrin receptor antibody reduced stroke injury." (PMID 23613937, 2013). "By controlling TFRC levels, NEDD4L can reduce iron uptake and suppress iron-dependent oxidative cell death pathways like ferroptosis after stroke." (PMID 38302612, 2024). "In mouse stroke models, we found METTL3 overexpression increased NEDD4L levels, enhanced TFRC ubiquitination and degradation, limited iron accumulation, and reduced oxidative damage and ferroptotic cell death, resulting in smaller infarct sizes and improved neurological function." (PMID 38302612, 2024).